GMEB1 (glucocorticoid modulatory element binding protein 1)
Description:
Acts as a DNA-binding transcriptional regulator involved in modulating the expression of genes responsive to glucocorticoid signaling. Specifically binds AT-rich DNA motifs known as glucocorticoid modulatory elements (GMEs), repressing or enhancing transcription depending on cellular context. Forms heterodimeric complexes with GMEB2, which enhances its DNA-binding specificity and transcriptional activity. This complex plays a critical role in the repression of glucocorticoid receptor (GR/NR3C1) transcriptional activity, acting as a negative modulator of glucocorticoid signaling. Regulates dopamine-enriched midbrain genes, including tyrosine hydroxylase/TH and the dopamine transporter SLC6A3, essential for dopamine signaling (By similarity). Also binds the transferrin receptor promoter. In the cytoplasm, inhibits caspase activation and neuronal apoptosis by stabilizing CFLARL and blocking pro-caspase 8 activation.
Synonyms: P96PIF; PIF96
Tractability: PROTAC: ubiquitination databases record sites on it; its protein half-life has been measured.
Gene: Protein-coding gene on chromosome 1 (28,668,280 to 28,719,353, forward strand). Ensembl gene ENSG00000162419.
Subcellular location: Nucleus; Cytoplasm
Subcellular location (Human Protein Atlas): Nucleoplasm
Gene Ontology:
Molecular function: Hsp27 protein binding; identical protein binding; protein binding; protein-macromolecule adaptor activity; RNA polymerase II cis-regulatory region sequence-specific DNA binding; sequence-specific double-stranded DNA binding; DNA-binding transcription activator activity, RNA polymerase II-specific; DNA-binding transcription factor activity, RNA polymerase II-specific; DNA binding; DNA-binding transcription factor activity; sequence-specific DNA binding
Biological process: negative regulation of apoptotic process; positive regulation of transcription by RNA polymerase II
Cellular component: cytoplasm; nucleoplasm; nucleus; chromatin
Genetic constraint (gnomAD): Loss-of-function variants: 1 observed, 31.52 expected, observed/expected ratio (o/e) 0.0317, 90% interval 0.01 to 0.15. The upper end of that interval is the gene's LOEUF score, 0.15, which puts it in group 1 of 6, group 1 being the genes least tolerant of losing a copy. Missense variants: 334 observed, 504.16 expected, observed/expected ratio (o/e) 0.66, 90% interval 0.61 to 0.73. Synonymous variants: 174 observed, 186.42 expected, observed/expected ratio (o/e) 0.93, 90% interval 0.82 to 1.06.
Homologues: Orthologues: chimpanzee GMEB1 (99% identical), macaque GMEB1 (99% identical), pig GMEB1 (99% identical), dog GMEB1 (99% identical), rabbit GMEB1 (98% identical), guinea pig GMEB1 (98% identical), rat Gmeb1 (95% identical), mouse Gmeb1 (95% identical), tropical clawed frog gmeb1 (59% identical), zebrafish gmeb1 (50% identical), Caenorhabditis elegans gmeb-2 (14% identical), Caenorhabditis elegans gmeb-3 (14% identical), and 2 more. Paralogues in human: GMEB2 (34% identical).
Diseases named in the same sentence as GMEB1 in open-access papers:
GMEB1 is named in the same sentence as 9 diseases in open-access papers, as found by Europe PMC text mining. Sharing a sentence is not in itself a finding about the gene and the disease. The quoted sentences say what the papers report.
non-small cell lung carcinoma (2 papers, 2019 to 2025). A group of at least three distinct histological types of lung cancer, including non-small cell squamous cell carcinoma, adenocarcinoma, and large cell carcinoma. "GMEB1 can promote the malignant proliferation and metastasis of HCC by promoting the transcription of the YAP1 promoter region; GMEB1 can also interact with USP40 to stabilize CFLARL in non-small cell lung cancer and inhibit cell apoptosis." (PMID 40625743, 2025). "Human non-small cell lung cancer cells and 293FT cells were used to investigate the function of GMEB1/USP40/CFLARL complex by WB, GST Pull-Down Assay, Immunoprecipitation, Immunofluorescence and Flow cytometry analysis." (PMID 31046799, 2019). "Additionally, GMEB1 inhibited the activation of pro-caspase 8 and apoptosis in non-small cell lung cancer (NSCLC) cell via CFLARL stabilization." (PMID 31046799, 2019).
neuroendocrine tumors (1 paper, 2022). "The opposite impact of TF score on the survival of NEL and NBL may attributed to BATF3, GMEB1 and REST, since NFIA and ZNF281 showed uniform influence on the survival of the two neuroendocrine tumors." (PMID 36713370, 2022).
cancer (1 paper, 2019). A tumor composed of atypical neoplastic, often pleomorphic cells that invade other tissues. "In the cytosol, GMEB1 interacts with HSP27, a protein chaperone with many critical functions in cancer invasion, metastasis, proliferation and apoptosis." (PMID 31046799, 2019).
infection (1 paper, 2019). The state of being infected such as from the introduction of a foreign agent such as serum, vaccine, antigenic substance or organism. "To ensure that the lack of Th or Dat protein signal was not due to cell death resulting from Gmeb1 knockdown, we compared the transcriptome of mDA neurons 2 weeks after infection with viruses expressing shGmeb1 or shScramble." (PMID 31175277, 2019).
tumor (1 paper, 2019). "In vivo data showed GMEB1 knockdown inhibited the A549 xenograft tumor growth, which also confirmed our results." (PMID 31046799, 2019). "A549 cells overexpressing green fluorescent protein and GMEB1 shRNA were used for tumor xenograft using female athymic nu/nu 4-week-old mice." (PMID 31046799, 2019). "Results show tumor growth was inhibited after GMEB1 knockdown compared with the control group." (PMID 31046799, 2019). "Downregulation of GMEB1 inhibited A549 xenograft tumor growth in vivo." (PMID 31046799, 2019).
GMEB1 also shares sentences with these, for which no sentence is quoted: neuroblastoma (1 paper); psychiatric disorder (1); schizophrenia (1); type 2 diabetes (1).